RNU1-15P (RNA, U1 small nuclear 15, pseudogene)
Synonyms: U1P11; RNU1P8
Gene: Small nuclear RNA gene on chromosome 7 (21,381,363 to 21,381,506, forward strand). Ensembl gene ENSG00000195024.
Homologues: Orthologues: chimpanzee U1 (94% identical), macaque U1 (85% identical), rabbit U1 (58% identical). Paralogues in human: RNU1-83P (80% identical), RNU1-1 (79% identical), RNU1-2 (79% identical), RNU1-27P (79% identical), RNU1-28P (79% identical), RNU1-3 (79% identical), RNU1-4 (79% identical), RNVU1-18 (79% identical), RNVU1-29 (79% identical), RNVU1-31 (79% identical), RNVU1-7 (79% identical), U1 (79% identical), and 134 more.